KIF18A (kinesin family member 18A)
Diseases named in the same sentence as KIF18A in open-access papers (continued):
Sharing a sentence is not in itself a finding about the gene and the disease.
cancer (continued). "Moreover elevated expression of KIF18A has been shown in other cancers to be associated with enhanced cell proliferation and predictive of poor prognosis." (PMID 28404951, 2017). "Furthermore, expression of KIF18A was associated with cancer grade and metastasis status and may facilitate cancer cell migration by deregulating microtubule stability." (PMID 32322170, 2020). "In addition, given the fact that KIF18A plays critical roles in modulating microtubule (MT) dynamics and mitosis, MTs and MT-associated proteins might also be significant drug targets for cancer chemotherapy." (PMID 25431949, 2014). "This selective dependency makes KIF18A-targeted therapy a promising option for HGSOC, as cells associated with this cancer harbor genomic alterations linked to CIN." (PMID 41369352, 2025). "Other studies have confirmed these observations, demonstrating that KIF18A inhibitors activate the spindle checkpoint, with cell death being highly selective for cancer cells exhibiting high CIN." (PMID 40227811, 2025). "KIF18A is overexpressed in several cancers, and its high expression correlates with worse prognoses." (PMID 41369352, 2025). "One promising target is the plus-end-directed motor protein KIF18A, which is uniquely essential for the division of certain cancers." (PMID 38279026, 2024). "It has been proposed that the altered microtubule dynamics in cancers with CIN render them more reliant on KIF18A function." (PMID 38279026, 2024). "Cancer cell lines with CIN features show preferential sensitivity to inhibition of KIF18A, leading to SAC activation, multipolarity, centrosome fragmentation and apoptosis." (PMID 38151625, 2024). "A positive correlation has also been established between KIF18A expression and Th2 for 33 types of cancer in the TCGA database (Th2 suppresses the anti-tumor immune response)." (PMID 39518001, 2024). "Next, we profiled the antiproliferative effects of AM-0277, AM-1882 and AM-9022 on the same panel of cancer cell lines used for our KIF18A-KD studies and included two additional cell models (HCC-1937 TNBC, OVCAR-5 HGSOC)." (PMID 38151625, 2024). "Our KIF18A inhibitors will serve as excellent tools to further explore CIN as a cancer-specific vulnerability and to address outstanding questions concerning KIF18A biology, SAC signaling and biomarker-discovery efforts." (PMID 38151625, 2024). "Collectively, these data suggest that AM-1882 faithfully phenocopies KIF18A gene-KO and -KD dependencies across cancer cell lines." (PMID 38151625, 2024). "Collectively, our results provide a rational therapeutic strategy for selective targeting of CIN cancers via KIF18A inhibition." (PMID 38151625, 2024). "Here, we provide evidence that selective inhibition of the KIF18A motor has promising preclinical activity across a subset of human cancer models." (PMID 38151625, 2024). "KIF18A is a regulator of the cell cycle acting on the G2/M phase, and if it is knocked down, the proliferation of cancer cells is inhibited." (PMID 38195458, 2024). "KIF18A-dependent cancer cells exhibit hallmarks of this SAC:APC/C imbalance, including a long metaphase-to-anaphase transition, and slow mitosis overall." (PMID 38279026, 2024). "Here, we show that inhibitors of the KIF18A motor protein activate the mitotic checkpoint and selectively kill chromosomally unstable cancer cells." (PMID 38151625, 2024). "Lastly, from a therapeutic perspective, this study provides the framework to explore the potential of KIF18A inhibitors for targeting CIN-driven human cancers." (PMID 38151625, 2024). "To investigate the determinants of KIF18A dependency in cancer, we used AM-1882, a highly specific small molecule KIF18A inhibitor (KIF18Ai) developed by Amgen Inc." (PMID 38279026, 2024).
cancer (continued). "Our KIF18A inhibitors have minimal detrimental effects on human normal somatic cells at concentrations that are well above the range required to kill cancer cells, distinct from other anti-mitotic agents." (PMID 38151625, 2024). "A cancer-specific dependency on the microtubule motor protein KIF18A therefore makes it an attractive therapeutic target." (PMID 38279026, 2024). "Here, using a small molecule inhibitor of KIF18A, we demonstrate that long mitotic delays and lethal errors in cell division drive cell death in KIF18A-dependent cancers." (PMID 38279026, 2024). "This increase in SAC signal is common among KIF18A-dependent and agnostic cancers but is exacerbated by increased ploidy." (PMID 38279026, 2024). "In mice, inhibition of KIF18A leads to robust anti-cancer effects with tumor regression observed in human HGSOC and TNBC models at well-tolerated doses." (PMID 38151625, 2024). "KIF18A KD caused a significant increase in pH3 positivity and PCM focus count in sensitive cancer cell lines." (PMID 38151625, 2024). "In summary, we describe here the discovery and characterization of KIF18A inhibitors with promising anti-cancer activity." (PMID 38151625, 2024). "This work provides a mechanistic model implicating altered APC/C activity and spindle assembly checkpoint (SAC) signaling in the cancer cell-specific dependence on KIF18A." (PMID 38279026, 2024). "A fraction of cancer cells are highly dependent on kinesin KIF18A function because of alterations in the ratio of APC/C and spindle assembly checkpoint (SAC) signals." (PMID 38279026, 2024). "Collectively, these data demonstrate that i.p.-administered KIF18A inhibitors have robust anti-cancer activity at well-tolerated doses in mice." (PMID 38151625, 2024). "KIF18A was positively or negatively correlated with the infiltration of 22 other immune cells in a majority of the cancers." (PMID 36830695, 2023). "We found that KIF18A was positively correlated with a stromal and immune score in three cancers and negatively in nine cancers, suggesting that KIF18A interacted with tumor cells and immune cells in tumors." (PMID 36830695, 2023). "GSEA analysis of KIF18A revealed that KIF18A was primarily involved in the cell cycle, homologous recombination, and DNA replication of some cancers." (PMID 36830695, 2023). "Bioinformatic analysis and immunohistochemical experiments confirmed that KIF18A was up-regulated in 27 tumors and was correlated with the T stage, N stage, pathological stage, histological grade, and Ki-67 index in many cancers." (PMID 36830695, 2023). "Our work confirmed the significant overexpression of KIF18A in 27 cancers from TCGA and GTEx databases." (PMID 36830695, 2023). "We discovered that KIF18A mainly participated in the cell cycle, homologous recombination, and DNA replication of most cancers." (PMID 36830695, 2023). "We note that small molecule inhibitors of KIF18A are being developed as a novel anti-cancer strategy." (PMID 37639469, 2023). "In our work, KIF18A expression was positively interrelated with regulatory genes of RNA methylation for several cancers." (PMID 36830695, 2023). "KIF18A was positively related to Th2 infiltration levels in 33 cancers, and the correlation coefficient was greater than 0.6 in 16 cancers." (PMID 36830695, 2023). "For instance, the mitotic kinesin, KIF18A has been shown to play a key role in maintaining bipolar spindle integrity and to be crucial for the survival of cancer cells with CIN." (PMID 36864125, 2023). "The mitotic kinesin, KIF18A, is required for proliferation of cancer cells that exhibit chromosome instability (CIN), implicating it as a promising target for treatment of a subset of aggressive tumor types." (PMID 37905069, 2023). "Depleting KIF18A led to centrosome fragmentation and spindle multipolarity that depended on dynamic microtubules in chromosomally unstable cancer cell lines, all of which have undergone WGD, but not in stable near-diploid cell lines." (PMID 37576603, 2023).
cancer (continued). "The overexpression of KIF18A in tumors increased the degree of credibility for KIF18A as a new target in therapies for these cancers." (PMID 36830695, 2023). "In some cancers, KIF18A expression was significantly and positively correlated with immune regulatory genes." (PMID 36830695, 2023). "Afterwards, ESTIMATE algorithms were utilized to calculate the relationship of KIF18A with stromal score and immune score for 33 cancer types." (PMID 36830695, 2023). "KIF18A is a member of the microtubule-associated wire (KIF) superfamily, which has been shown to influence the progression of various cancers." (PMID 35464837, 2022). "18A (KIF18A) is a microtubule-based motor protein that is dysregulated and involved in the progression of multiple human cancers." (PMID 35464837, 2022). "It is noteworthy that some recent studies have revealed that KIF18A is closely related to the occurrence, development, invasion, and metastasis of various malignant tumours." (PMID 35591854, 2022). "Paclitaxel treatment causes an increase in multipolar spindles in both somatic diploid cells and aneuploid cancer cells, whereas KIF18A KD preferentially affected spindle morphology in the CIN cells tested here." (PMID 33619254, 2021). "In particular, multiple types of cancer display elevated levels of Kif18A, which suppresses the amplitude of chromosome oscillation." (PMID 34572757, 2021). "Inhibitors for various mitotic motor proteins that alter chromosome dynamics, such as Eg5, CENP-E, and Kif18A, are now under investigation for the efficacy against cancer cells." (PMID 34572757, 2021). "Kinesin proteins, including KIF18A, are often deregulated in many types of cancers and are thought to play critical roles in cancer progression." (PMID 30872592, 2019). "Studies have reported that KIF18A is highly expressed in many malignant tumours and is involved in the occurrence and development of tumours, but its mechanism is still unclear." (PMID 29466986, 2018). "In this study, we found that the expression of KIF18A in cancer tissues was higher than that of adjacent tissues." (PMID 29466986, 2018). "We infer that high expression of KIF18A can promote the proliferation of cancer cells and that the expression level of KIF18A is positively related to the invasiveness of different cancer cell lines." (PMID 29466986, 2018). "We found that PJ34, Phen and Tiq-A modify kinesins (HSET/kifC1 and kif18A) and NuMA (nuclear mitotic apparatus protein) in a variety of human cancer cells." (PMID 28209915, 2017). "We found that the phenanthrenes, PJ34, Phen and Tiq-A, prevent the post-translational modifications of NuMA, HSET/kifC1 and Kif18A exclusively in human cancer cells." (PMID 28209915, 2017). "Consistent with its potential oncogenic role, depletion of Kif18A inhibits cancer cell growth both in vitro and in vivo." (PMID 25884224, 2015). "Ablation of Kif18A reduces cancer cell proliferation, migration and invasion, and promotes cell apoptosis through negative regulation of the PI3K-AKT signaling axis." (PMID 25884224, 2015). "Kinesin proteins, including Kif18A, are often deregulated in many types of cancers and are thought to play a critical role in cancer progression." (PMID 25884224, 2015). "In addition, a comprehensive pan-cancer analysis reveals that KIF18A is correlated immune infiltration and immune checkpoint genes in a majority of cancers." (PMID 40175357, 2025). "Indeed, a variety of studies reveal that KIF18A expression is correlated with immune infiltration in cancers." (PMID 40175357, 2025). "Notably, one inhibitor, GSC000190, appears to exhibit anti-cancer efficacy in tumours resistant to cisplatin and olaparib, highlighting the potential utility of targeting KIF18A in the context of therapy resistance, which is often associated with CIN." (PMID 40002279, 2025). "KIF18A plays an important role in the tumorigenesis of various cancers." (PMID 40175357, 2025).
cancer (continued). "Furthermore, some Kinesin family members, like KIF2C, KIF20A, KIF18A, and KIF15, have been linked to cancer progression and potentially to resistance against hormone-based therapies." (PMID 40869915, 2025). "Moreover, aneuploid cancer cells are particularly vulnerable to KIF18A inhibition, while KIF18A overexpression increases the sensitivity to spindle assembly checkpoint inhibition." (PMID 40175357, 2025). "For instance, using the sequencing data from nearly 10,000 primary human cancer samples and more than 600 cancer cell lines, KIF18A is found to be a genetic vulnerability for whole-genome doubling cancer cells and silencing KIF18A induces mitotic errors and growth arrest." (PMID 40175357, 2025). "Given that Cdk1 is a key kinase that activates the SAC and that inhibiting Wee1 extends mitosis in a SAC-dependent manner, it can be hypothesized that combining Wee1 and Kif18A inhibition may potentiate therapeutic effectiveness against aneuploid cancers." (PMID 39610707, 2024). "Recently, suppression of Anaphase-Promoting Complex/Cyclosome-Cell Division Cycle 20 (APC/C-CDC20) activity using CRISPR/Cas9 mutagenesis has been reported to increase sensitivity to Kinesin Family 18a (KIF18a) inhibition, which functions to suppress multipolar mitotic spindles in cancer cells." (PMID 38928036, 2024). "The kinesin KIF18A has emerged as an important new drug target, but why ~25% of cancers are addicted to this protein remains unclear." (PMID 38279026, 2024). "KIF18A is a regulator of the cell cycle that stimulates the proliferation of cancer cells." (PMID 38195458, 2024). "Although loss of Kif18A function causes micronuclei formation, it appears to be rather tolerated by euploid cells and inactivating mutations in Kif18A have been shown to produce micronuclei in mice without leading to cellular transformation or cancer." (PMID 39610707, 2024). "Importantly, the sensitivity profile of AM-1882 aligns with KIF18A-KD and -KO gene dependency scores across cancer cell lines, suggesting that the mode of action of AM-1882 is chiefly driven by inhibition of KIF18A." (PMID 38151625, 2024). "Nevertheless, Kif18A does appear to be essential for survival of aneuploid cancer cells, perhaps by preventing unbearable chromosome mis-segregation in cells with more complicated spindle architecture, and is a vulnerability target for certain aneuploid cancers." (PMID 39610707, 2024). "Considering the relevance of Kif18A for survival of aneuploid cancer cells and the potential therapeutic targeting of both Kif18A and Wee1, these findings could also be relevant for cancer therapy." (PMID 39610707, 2024). "KIF18A-inhibitor treatment showed inhibition of DNA synthesis in both normal cell types that was well above the effective concentration (>20-fold) in sensitive cancer cell lines." (PMID 38151625, 2024). "However, the majority of previous research focused only on the function of KIF18A in a certain cancer; pan-cancer analyses on the prognostic significance and biological function of KIF18A are rarely carried out." (PMID 36830695, 2023). "We discussed KIF18A genetic alterations in pan-cancer using the cBioPortal database." (PMID 36830695, 2023). "We used CancerSEA and GSEA to perform pan-cancer functional analyses of KIF18A." (PMID 36830695, 2023). "The TIMER database was used to analyze the expression of KIF18A in pan-cancer and normal tissues." (PMID 36830695, 2023). "KIF18A has recently emerged as a promising cancer drug target." (PMID 37639469, 2023). "KIF18A can thus be used as a new drug target for anti-cancer immunotherapy." (PMID 36830695, 2023). "We chose OS, DSS, and PFI to investigate the prognosis of KIF18A in pan-cancer." (PMID 36830695, 2023).
cancer (continued). "The sensitivity of cancer cells with severe karyotypic abnormalities to KIF18A or SAC inactivation may be due to increased burden of supernumerary chromosomes on assortment and segregation in mitosis." (PMID 37639469, 2023). "KIF18A expression levels were positively associated with immunocyte infiltration, immune regulatory genes, immune checkpoints, TMB, MSI, MMRs, DNA methylation, RNA methylation, and drug sensitivity in certain cancers." (PMID 36830695, 2023). "We propose that combining PLK1 inhibitors with KIF18A inhibitors may prove particularly effective in treating cancers with complex karyotypes." (PMID 37639469, 2023). "Now, we know that the regulation of KIF18A plays an important role in many cancers." (PMID 35464837, 2022). "Moreover, in recent years, accumulating evidence has demonstrated that KIF18A is highly expressed in a variety of human malignant tumours and is widely involved in the occurrence, development, and outcome of tumours." (PMID 35591854, 2022). "Whether lowering CIN level by Kif18A depletion through enhancing chromosome oscillation acts synergistically with spindle disruption for cancer therapy is an interesting possibility to be examined." (PMID 34572757, 2021). "Importantly, the dysregulation or deletion of KIF18A results in longer spindles and aberrant chromosome segregation, which contribute to the initial onset of cancer." (PMID 35153752, 2021). "In fact, elevated KIF18A expression was observed in several human cancers." (PMID 31392101, 2019). "Therefore, KIF18A represents a promising target for therapeutic interventions in CIN+ cancers." (PMID 41369352, 2025). "It remains unclear, however, what features distinguish KIF18A-dependent and agnostic cancer cells." (PMID 38279026, 2024). "Thus, KIF18A may potentially become a new prognostic marker for many types of cancer, including endometrial cancer." (PMID 39518001, 2024). "Not all cancers require KIF18A, however, and the determinants underlying this distinction remain unclear." (PMID 38279026, 2024). "Moreover, KIF18A was positively correlated to m6A, m5C, and m1A regulatory genes in most cancers." (PMID 36830695, 2023). "KIF18A might have affected the prognosis of cancer patients through methylation." (PMID 36830695, 2023). "KIF18A is a druggable enzyme that may synergize with PLK1 inhibition in cancer treatments." (PMID 37639469, 2023). "However, few pan-cancer analyses have been performed on KIF18A to date." (PMID 36830695, 2023). "Perhaps KIF18A might have other roles in other kinds of cancers." (PMID 35464837, 2022). "Preclinical work demonstrating greater efficacy of CENPE, Eg5, and KIF18A inhibitors in aneuploid, tetraploid, and CIN-positive cancer models supports this concept." (PMID 40002279, 2025). "In CIN+ cancers such as HGSOC, characterized by high aneuploidy and CIN, KIF18A is critical for managing microtubule dynamics and ensuring accurate cell division." (PMID 41369352, 2025). "Depletion of KIF18A has been shown to induce excessive CIN and death of genomically unstable cancer cells." (PMID 40002279, 2025). "Second, we uncover the following important genes: KIF18A, PABPC1, and SPIC, which are consistent with previous cancer studies." (PMID 40286292, 2025). "To further study this differential dependency on KIF18A, we performed western blot analysis (WBA) on the cancer cell line panel after treatment with KIF18A, EG5 or NTC siRNA." (PMID 38151625, 2024). "We report the discovery and characterization of potent and selective small-molecule inhibitors of KIF18A motor activity and demonstrate promising activity toward CIN cancers." (PMID 38151625, 2024). "Second, we uncover the following important genes: KIF18A, CCDC19, and PABPC1, which are consistent with previous cancer studies." (PMID 39416165, 2024).